HMGB1 (high mobility group box 1)
Diseases named in the same sentence as HMGB1 in open-access papers (continued):
Sharing a sentence is not in itself a finding about the gene and the disease.
ovarian cancer (continued). "We tested the effect of four compounds, used in ovary-cancer therapy in the expression of the genes HMGB1, HMGB2, MIEN1 and NOP53 in cultured cancerous SKOV-3 cells and in non-cancerous IOSE-80 ovarian cells." (PMID 32867128, 2020). "Low expression of HMGB1 was protective and in a multivariate model HMGB1 expression was shown to be an independent predictor of poor survival in ovarian cancer (p=0.006)." (PMID 29254158, 2017). "In the present study, therefore, we investigated the plasma levels of HMGB1 during PPV in patients with recurrent ovarian cancer." (PMID 28536706, 2017). "There is an important need to understand the context-dependent role of HMGB1 as either an anti- or pro-tumorigenic protein in ovarian cancer." (PMID 29254158, 2017). "In the present study, therefore, we investigated the plasma levels of HMGB1 in patients with ovarian cancer treated with peptide vaccination." (PMID 28536706, 2017). "Our results indicate that high expression of HMGB1 is deleterious in ovarian cancer reducing the overall mean survival time (from 104 months in low/absent expressing tumours to 56 months in high expressing tumours)." (PMID 29254158, 2017). "NAC-1 knockdown experiments in ovarian cancer cell lines treated with cisplatin resulted in a reduction of cisplatin/HMGB1 induced autophagy and an increase in cytotoxicity of ovarian cancer cells." (PMID 29254158, 2017). "The mechanism by which HMGB1 expression is deleterious for ovarian cancer patients is currently unclear." (PMID 29254158, 2017). "In the present study, we investigated the plasma levels of HMGB1 during personalized peptide vaccination in patients with recurrent ovarian cancer." (PMID 28536706, 2017). "Nucleus accumbens-1 (NAC1), a nuclear factor belonging to the BTB/POZ gene family, also modulates sensitivity of ovarian cancer cells to cisplatin by altering the HMGB1-mediated autophagic response." (PMID 26682011, 2016). "Our work unveils the lactate-CREB1 K122la-HMGB1-NETs axis as a metabolic-epigenetic-immune driver of cisplatin resistance and provides a promising nanomedicine strategy for overcoming treatment resistance in ovarian cancer." (PMID 42212318, 2026). "The ability of HMGB1 to promote angiogenesis was also observed in ovarian cancer." (PMID 38725632, 2024). "Lastly, studies with a higher number of ovarian cancer cases in early stages will be needed to evaluate the potential of HMGB1 in the early detection of ovarian cancer, as HMGB1 expression in ovarian cancer tissue has been reported to increase in advanced stages." (PMID 37894448, 2023). "In vivo experiments showed that C-MYC could promote tumorigenesis and immune evasion in ovarian cancer cells through inhibiting HMGB1 release induced by NCOA4-mediated ferroptosis." (PMID 36552889, 2022). "The Western blot assay revealed that C-MYC could reduce HMGB1 release in ovarian cancer cells through the NCOA4 axis." (PMID 36552889, 2022). "The SIRT1/HMGB1 axis may therefore be a key therapeutic target for inhibiting ovarian cancer migration, thus attenuating the progression of this disease." (PMID 36081910, 2022). "Western blot assays revealed that in C-MYC-over-expressed ovarian cancer cells, extracellular free HMGB1 content significantly decreased, while NCOA4 up-regulation could reverse this change." (PMID 36552889, 2022). "This study reports the HMGB1 interactomes in prostate and ovary cancer cells lines." (PMID 34572914, 2021). "HMGB1 also induces migration, invasion and angiogenesis in ovarian cancer." (PMID 33711197, 2021). "Using tissue microarrays of primary ovarian cancers combined with a comprehensive database of clinicopathological variables, the expression of HMGB1 was assessed by immunohistochemistry in two independent cohorts (n=194 and n=360) using a monoclonal antibody specific for HMGB1." (PMID 29254158, 2017). "Therefore, future functional studies should determine the mechanism of HMGB1 function in ovarian cancer." (PMID 29254158, 2017).
ovarian cancer (continued). "The presence of circulating HMGB1 in patients with ovarian cancer has been reported, and the levels were significantly higher than those in patients with benign ovarian tumors or healthy donors, and the levels in recurrent patients were higher than those in nonrecurrent patients." (PMID 28536706, 2017). "If this can be determined, then strategies designed to modulate the HMGB1 pathway may provide a rational approach in the therapeutic targeting of ovarian cancer." (PMID 29254158, 2017). "Therefore, HMGB1 protects ovarian cancer cells from chemotherapy induced apoptosis by shifting the balance from apoptosis to autophagy." (PMID 29254158, 2017). "Our work using two independent cohorts of ovarian cancer patients demonstrates that HMGB1 may represent an independent marker of poor prognosis." (PMID 29254158, 2017). "Indeed, our data support the results of a recent small scale study of ovarian cancer patients (n=74 patients) which confirmed that high HMGB1 tissue expression correlated with progression free survival." (PMID 29254158, 2017). "HMGB1 is considered a biomarker for ovarian cancer and increased levels of interleukin-8 protein (IL-8) and HMGB1 correlate with poor prognosis in prostate and ovarian cancer cells." (PMID 26682011, 2016). "The proteins HMGB1, HMGB2, HSC70, GRP58, and GAPD form a nuclear complex, which alters DNA conformation, and they have been associated in vivo with resistance to chemotherapeutic drugs in ovarian cancer patients." (PMID 26682011, 2016). "Targeting HMGB1 by RNA interference inhibits ovarian cancer growth and metastasis." (PMID 26682011, 2016). "In the analyses of receiver operating characteristics, both HMGB1 and sRAGE could distinguish patients with ovarian cancer from healthy women (area under the curve (AUC) 0.77 and 0.65), benign diseases (AUC 0.72 and 0.61) or all non-malignant cases (AUC 0.74 and 0.63)." (PMID 37894448, 2023). "Therefore, the combination of these established biomarkers with HMGB1 and/or the HMGB1/sRAGE ratio may improve such detection, thereby leading to earlier diagnosis and resulting in better prognosis for patients with ovarian cancer." (PMID 37894448, 2023). "However, as this study was intended as an exploratory approach to evaluate a possible use of HMGB1 and sRAGE as diagnostic tools in ovarian cancer, no prospective or matched design was used." (PMID 37894448, 2023). "It was shown that HMGB1 may be a future marker in hormone-related cancer including ovarian cancer." (PMID 37894448, 2023). "In addition FIGO stage (p<0.001) and response to chemotherapy (p<0.001) also remained independent predictors of patient survival suggesting that HMGB1 may be a useful independent prognostic marker in ovarian cancer." (PMID 29254158, 2017). "The prognostic value of HMGB1 in ovarian cancer remains unclear." (PMID 29254158, 2017). "As high levels of HMGB1 expression are likely to render ovarian cancer cells resistant to chemotherapy, therapies targeting the HMGB1 axis may be appropriate in the treatment of ovarian cancer patients." (PMID 29254158, 2017). "Deacetylation and inhibition the cytosolic release of HMGB1 by sirtuin 1 (SIRT1) inhibits migration and angiogenesis in ovarian cancer cells." (PMID 38725632, 2024). "DAMPs such as HMGB1, CRT, ATP, and PGE2 are created when ferroptosis occurs in ovarian cancer cells." (PMID 39192972, 2024). "In this study, the immunogenic and inflammatory proteins HMGB1, sRAGE, PD1 and PD-L1 were investigated as possible biomarkers in ovarian cancer." (PMID 37894448, 2023). "Paclitaxel, but not carboplatin, was found to induce ICD through the release of HMGB1 and activation of TLR-4-dependent and -independent pathways in ovarian cancer." (PMID 35986757, 2023). "In this respect, high-mobility group box 1 protein (HMGB1) and receptor for advanced glycation end products (RAGE) are two potential tumor markers capable of improving the diagnosis and treatment of ovarian cancer." (PMID 37894448, 2023).
ovarian cancer (continued). "Paclitaxel treatment resulted in the release of HMGB1 and activation of TLR-4-dependent and -independent pathways in ovarian cancer." (PMID 35366537, 2022). "In the ovarian cancer cell line SKOV-3, HMGB1 silencing diminishes the expression of VEGF and CXCL12, revealing its involvement in angiogenesis." (PMID 32867128, 2020). "HMGB1 and HMGB2 genes were silenced in SKOV-3 and PEO1 EOC cell lines and levels of mRNA from 4 detected interacting partners of HMGB1 or HMGB2 in ovary cancer, COMMD1, MIEN1, NOP53 and ZNF428, were analyzed by qRT-PCR as explained in Materials and Methods." (PMID 32867128, 2020). "With these precedents we decided to investigate the role of HMGB1, HMGB2, MIEN1 and NOP53 in cell viability as well as in response and sensitivity to drugs currently used in ovarian cancer therapy." (PMID 32867128, 2020). "Considering that HMGB1 and HMGB2 proteins have been associated to drug resistance during cancer treatment we also reviewed available literature to see whether the proteins detected in our interactome study could also be related to this unfavorable event in ovary cancer treatment." (PMID 32867128, 2020). "Expression changes of HMGB1, HMGB2, MIEN1 and NOP53 genes have been evaluated in response to drugs usually employed in ovarian cancer treatments: bevacizumab, olaparib, paclitaxel or carboplatin." (PMID 32867128, 2020). "HMGB1 and HMGB2 expression is augmented in a number of tumors, such as human gastric, breast, and ovarian cancer (and refs. therein)." (PMID 33076532, 2020). "We have experimentally probed that HMGB1, HMGB2 and two of their partners, MIEN1 and NOP53 are also involved in the response of ovarian cancer cells to several drugs used in chemotherapy against EOC." (PMID 32867128, 2020). "We have determined the first interactome of HMGB1 and HMGB2 in epithelial ovarian cancer (the EOC-HMGB interactome)." (PMID 32867128, 2020). "HMGB1 and HMGB2 interact with each other and they have common interactors like the nuclear hormonal receptors which are deregulated in prostate and ovarian cancers." (PMID 26682011, 2016). "Carboplatin‐resistant ovarian cancer models reveal that HMGB1 boosts NER and HRR by recruiting repair factors such as XPA and RAD51—siRNA‐mediated HMGB1 silencing induces accumulated DNA damage, elevates apoptosis, and reduces carboplatin IC50 by nearly an order of magnitude." (PMID 41354099, 2025). "Both HMGB1 and sRAGE have been studied concerning their application in ovarian cancer, yet results have not been conclusive so far." (PMID 37894448, 2023). "Moreover, the pyroptotic phenotype of ovarian cancer cells along with the release of LDH and HMGB1 were observed, indicating the leakage of cells." (PMID 36016611, 2022). "Interestingly, we have shown in our study that HMGB1, HMGB2 and their EOC-HMGB-interactome partners MIEN1 and NOP53 are involved in the response to carboplatin, or drugs nowadays used in ovarian cancer treatment, such as bevacizumab, olaparib and paclitaxel." (PMID 32867128, 2020). "To extend the in vivo discovery in cancer cells, we have undertaken a different HMGB1-interactome analysis approach based on immunoprecipitation (IP) and mass spectrometry (MS) in PC-3 and SKOV-3 cell lines that represent models for prostate and ovarian cancer, respectively." (PMID 34572914, 2021). "Indeed, no data are available about the role of HMGB1 or HMGB2 in the resistance to olaparib or bevacizumab in the treatment of ovarian cancer." (PMID 32867128, 2020). "However, to date no studies have explored how HMGB1 may regulate the bioenergetics of ovarian cancer cells and this will be a fruitful area for further investigation." (PMID 29254158, 2017).
ovarian cancer (continued). "In this study, concentrations of the immunogenic biomarkers HMGB1, sRAGE, PD1 and PD-L1 were determined in the blood samples of 231 women with ovarian cancer, inflammation, cysts, other benign diseases or without any diagnosed severe disease." (PMID 37894448, 2023). "Secondly, the survival analyses of patients with ovarian cancer clearly indicated that the expression levels of CALR, PDIA3, ANXA1, HMGB1, IFNAR1, and PANX1 had no significant influence on overall survival (OS) and disease-free survival (DFS)." (PMID 35991556, 2022). "Firstly, the expression analyses of patients with ovarian cancer showed that the expression levels of CALR and PDIA3 in ovarian cancer were significantly up-regulated in compared with normal control tissues, while the expression of PANX1, ANXA1, HMGB1, and IFNAR1 were nonsignificant." (PMID 35991556, 2022). "The initial diagnosis of ovarian cancer often occurs in FIGO stages III or IV due to the lack of early symptoms in localized stages, hence resulting in a relatively large tumor mass at the time of diagnosis and a consistently higher secretion of HMGB1 with subsequent depletion of sRAGE." (PMID 37894448, 2023).
leukemia (49 papers, 2013 to 2025). A malignant (clonal) hematologic disorder, involving hematopoietic stem cells and characterized by the presence of primitive or atypical myeloid or lymphoid cells in the bone marrow and the blood. "What’s more, we found that poly (ADP-ribosylation) of HMGB1 facilitated its acetylation and promoted HMGB1 translocation-associated chemotherapy-induced autophagy in leukemia cells." (PMID 34933679, 2021). "There are also several studies indicating that HMGB1 plays an important role in leukemia pathogenesis and its upregulation is strongly associated with chemotherapy resistance by regulating cell autophagy." (PMID 33128580, 2021). "Study showed that poly (ADP-ribosylation) of HMGB1 facilitated its acetylation and promoted HMGB1 translocation-associated chemotherapy-induced autophagy in leukemia cells in which acetylation of HMGB1 is the most crucial process." (PMID 34933679, 2021). "Recently, the poly-ADP-ribosylation of HMGB1 was found to facilitate its acetylation and promoted HMGB1 translocation-associated chemotherapy-induced autophagy in leukemia cells." (PMID 32660524, 2020). "HMGB1 contributes to the pathogenesis of various human diseases including leukemia and maybe relevant for understanding the mechanisms underlying DS and its therapy." (PMID 28404891, 2017). "Interference with this pathway prevents HMGB1 export and diminishes autophagy, thereby restoring sensitivity to chemotherapeutic drugs in leukemia." (PMID 41465435, 2025). "When leukemia cells are stimulated by cytotoxicity produced by chemotherapeutic drugs, they release HMGB1 from the cells to resist the damage." (PMID 40969278, 2025). "And after the addition of HMGB1-neutralizing antibody treatment, leukemia cells have increased sensitivity to chemotherapy." (PMID 40969278, 2025). "HMGB1 plays an important role in the pathogenesis of leukemia, and its upregulation is closely related to chemotherapy resistance by regulating autophagy." (PMID 40130394, 2025). "Based on the HMGB1 study with leukemia cells, this suggests cells treated with Gemcitabine would have a reduced rate of ferroptotic cell death." (PMID 37568677, 2023). "Stemphol, a natural dialkyl resorcinol extracted from Stemphylium globuliferum, induced caspase-independent cell death and released high-mobility group box 1 (HMGB1) in leukemia cells." (PMID 36899361, 2023). "High-mobility group box 1 (HMGB1), a leukemia pathogenic gene, inhibits LPO via the RAS/MAP kinase (MAPK) pathway, promoting ferroptosis resistance." (PMID 38239395, 2023). "High mobility group box 1 regulates ferroptosis by the RAS-JNK/p38 pathway in the pathogenesis of leukemia and chemotherapy resistance." (PMID 36352396, 2022). "Both in vivo and ex vivo experiments in leukaemia cells have shown that high mobility group box-1(HMGB1) is a key regulatory molecule in erasure-induced ferroptosis." (PMID 35990689, 2022). "Human leukemia cells resist doxorubicin and vincristine by secreting high mobility group box 1 (HMGB1), responsible for overexpressing LC3-II in cancer cells." (PMID 35814444, 2022). "To figure out extracellular HMGB1’s function on leukemia cells, we incubated the cells with extracellular HMGB1 for 24 h before treated with ADM." (PMID 34933679, 2021). "Recently, high mobility group box 1 was demonstrated to regulate ferroptosis through a RAS-JNK/p38-dependent pathway in leukemia." (PMID 34867747, 2021). "As a positive regulator of autophagy, intracellular HMGB1 interacts with Beclin 1 in leukemia cells, leading to autophagosome formation." (PMID 34445246, 2021). "And it is reported that the expression of HMGB1 in primary and relapsed leukemia was much higher than healthy people and patients with complete remission." (PMID 34933679, 2021).